INS (insulin)
Diseases named in the same sentence as INS in open-access papers (continued):
Sharing a sentence is not in itself a finding about the gene and the disease.
diabetes (continued). "On the contrary, when the insulin signal is reduced like in obesity or diabetes, the insulin-independent Ras pathway can be useful to improve the glucose disposal." (PMID 26184280, 2015). "The broad implications of his discoveries of the pathways of insulin biosynthesis and secretion placed the University of Chicago at the forefront of diabetes research." (PMID 25617020, 2015). "In view of the crucial role of IRS-1 in insulin signaling, polymorphisms in the IRS1 gene were considered to have an impact on IRS-1 function and association with diabetes, especially those nonsynonymous mutations." (PMID 25978640, 2015). "We recently reported that glycated albumin (GA) is increased in subjects with longer duration of diabetes and with decreased insulin secretory function." (PMID 26484352, 2015). "Mice in which the genes for growth hormone (GH) or GH receptor (GHR−/−) are disrupted from conception are dwarfs, possess low levels of IGF‐1 and insulin, have low rates of cancer and diabetes, and are extremely long‐lived." (PMID 26268661, 2015). "In the present registry, insulin was predominantly used in patients with long-standing diabetes, higher blood glucose values, and a higher prevalence of microvascular disease, indicating a more advanced disease stage." (PMID 25645672, 2015). "Several animal studies have suggested that targeting higher serum insulin levels and insulin resistance is an effective strategy for inhibiting obesity- and diabetes-related liver tumorigenesis." (PMID 25879666, 2015). "Many of the metabolic derangements known to occur in diabetes, including hyperglycemia, excess free fatty acid liberation, and insulin resistance, mediate abnormalities in endothelial cell function." (PMID 33530149, 2015). "Because the prevalence of diabetes is increasing and insulin is used to treat millions of diabetic patients, it is clinically important to clarify the effects of insulin use on the risk for breast cancer." (PMID 26171401, 2015). "On the other hand, some patients would have to change insulin type if they had a low postprandial C-peptide concentration such as case 10 who was diagnosed with diabetes for six years." (PMID 25961056, 2015). "Due to this dietary regimen, NZO mice become obese and insulin resistant, but are protected from developing diabetes." (PMID 25527001, 2015). "Since metformin has been reported to partially reverse the insulin-resistance in diabetes mellitus type 2, we also investigated the effect of the insulin-sensitizing drug rosiglitazone on oxidative stress-induced apoptosis." (PMID 26038701, 2015). "As a result, staff nurses reported that they were primarily planning for education of insulin injections (63.2%) for patients and a regimen of oral anti-diabetes (60.9%), for patients during their discharge period (Table-I)." (PMID 26150859, 2015). "Mounting evidence including the rescue of insulin sensitivity on FoxO1 haploinsufficient mice and the induction of diabetes in FoxO1 gain‐of‐function mutant mouse shed light on these pathogenetic roles of FoxO proteins." (PMID 26176567, 2015). "The Canadian National Population Health Survey (a large, representative longitudinal study) used self-reporting of diabetes status, insulin treatment and frequency of RTAs." (PMID 28702227, 2015). "High concentrations of hydrogen peroxide (H2O2) have been shown to directly induce insulin signaling (phosphatidylinositol-3-kinase dependent pathway) leading to insulin resistance prior to the onset of diabetes." (PMID 25821809, 2015). "Because of the suspicion that pancreatic islets are the source of a hormone that presumably prevents diabetes, Edward Albert Sharpey-Schafer, a British physiologist and one of the founders of endocrinology, called this hypothetical hormone insulin." (PMID 26180777, 2015). "The most commonly used glucose lowering drugs in patients with previously known diabetes were metformin (57 %), insulin (27 %), sulfonylurea (25 %) and DPP-4 inhibitor (7 %)." (PMID 26427624, 2015).
diabetes (continued). "Diabetes affects nearly 350 million people worldwide and of these, 95% of patients have type 2 diabetes, suffering from impaired insulin sensitivity and/or impaired insulin secretion." (PMID 26046931, 2015). "Among the agents, only use of insulin was independently associated with SDNN (β = −0.224, p = 0.034) together with plasma leptin (β = −0.256, p = 0.042) and duration of diabetes (β = −0.223, p = 0.041)." (PMID 26338087, 2015). "T2DM which constitutes the vast majority of diabetes is a heterogeneous disorder characterized by impairment of insulin sensitivity, followed by the inability of pancreatic β cells to compensate for insulin resistance (pancreatic beta cell dysfunction)." (PMID 26003803, 2015). "Type 2 diabetes mellitus (T2DM) is a metabolic disease characterized by hyperglycemia that can occur as a result of impaired insulin secretion, insulin resistance in peripheral tissues and increased hepatic glucose output." (PMID 25897419, 2015). "Model selection for CVD mortality included fasting glucose, HbA1c, CAC, pulse pressure, HDL, triglycerides, eGFR, UACR, QT interval, diabetes duration, BMI, high blood pressure medication use, insulin use, history of CVD, educational attainment, WHR, and IMT." (PMID 26146522, 2015). "Patients DK-1 and DK-3 had a diagnosis of type 1 diabetes mellitus, but their compliance with insulin therapy was poor." (PMID 26299943, 2015). "Many diabetes patients have to take medication for the rest of their lives to improve their insulin uptake and to prevent or delay the development of complications and premature death." (PMID 25890162, 2015). "South Asian participants had lower insulin sensitivity over all ages, confirming findings from the literature that shows decreased insulin sensitivity from a young age in South Asians, decades before the manifestation of diabetes." (PMID 25431266, 2015). "In diabetes mellitus because of the absence or insufficient sensitivity to insulin, GLUT 4, is decreased." (PMID 26475130, 2015). "Diabetes was found in 19 (7%) participants,with three subjects using both insulin and oral hypoglycemic drugs, and 16 were takingonly oral drugs." (PMID 26132095, 2015). "If the proposed method is feasible and effective, the endogenous secretion system of insulin would be re-established in patients with diabetes." (PMID 26714858, 2015). "We examined how the patients performed insulin injections, meal planning and appropriate diet, maintaining self-check blood glucose monitoring, and exercising regularly which are important in diabetes management." (PMID 26005688, 2015). "Exogenous insulin treatment can prevent the diabetes induced changes in astrocyte glutamate uptake and GFAP expression in the brain." (PMID 25759824, 2015). "T2DM remission was observed to be negatively correlated with age, diabetes duration, insulin use, and HbA1c levels." (PMID 25103403, 2015). "The reasons for diabetes accelerated atherosclerosis are not completely understood, although hyperglycemia, dyslipidemia, and defective insulin signaling have been suggested to play a role." (PMID 25946019, 2015). "Of the 940 participants, 83 (8.8%) reported diabetes (11 of them reported insulin therapy, suggesting possible Type 1 diabetes), whereas 117 (12.4%) had HbA1c levels equal to or above the cut-off of diabetes diagnosis." (PMID 25603418, 2015). "Some Hispanic Americans reported misconceptions that insulin therapy was harmful, held fatalistic beliefs, used folk healers and alternative treatments for diabetes management." (PMID 26383535, 2015). "Switching of the basal insulin regimen from glargine or detemir to degludec significantly improved the QOL of patients with type 2 diabetes mellitus who were receiving BOT, by reducing mental stress or anxiety about their treatment." (PMID 26819737, 2015). "This trophic effect of diabetes is related to hyperglycemia, since insulin therapy showed tissue normalization." (PMID 26659064, 2015).
diabetes (continued). "Endometrial cells have differentiated into morphologically and functionally glucose-responsive insulin secreting cells, providing a potential therapeutic strategy for diabetes." (PMID 26253932, 2015). "We have reported that such patients manage their diabetes by using insulin-sensitizing agents other than metformin and are also commonly prescribed insulin." (PMID 25664662, 2015). "While the American Diabetes Association (ADA) and European Association for study of Diabetes (EASD) suggest basal insulin as an initial preferred strategy, the International Diabetes Federation (IDF) recommends both premixed and basal insulin." (PMID 25874190, 2015). "The study also included heterogeneous group of patients with variable diabetes duration and on variable number of antihyperglycemic medications including insulin." (PMID 26114120, 2015). "The strongest risk factors for DR that are consistently described in the literature include diabetes duration, glycemic control, insulin treatment and hypertension." (PMID 25925666, 2015). "The use of insulin, more frequently perceived hyperglycemic episodes and better diabetes knowledge increased the odds of becoming a persistent user." (PMID 26086272, 2015). "Type 2 diabetes (T2D), defined as hyperglycemia resulting from compromised insulin utilization (insulin resistance, IR) coupled with insufficient compensatory insulin production, is the common form of diabetes mellitus." (PMID 26202330, 2015). "Therapies currently available for the treatment of the different types of diabetes include insulin and various hypoglycemic agents such as sulphonylureas and biguanides." (PMID 25859777, 2015). "For example, insulin dose calculator software is helpful for patients with diabetes to determine bolus insulin doses." (PMID 28702234, 2015). "We explored the accuracy and clinical suitability of apps for calculating medication doses, focusing on insulin calculators for patients with diabetes as a representative use for a prevalent long-term condition." (PMID 25943590, 2015). "Insulin resistance was treated with lifestyle intervention and metformin, and diabetes with the addition of glitazones, glucagon-like peptide 1 agonists, and/or insulin." (PMID 26066530, 2015). "The cost of drugs used for diabetes treatment (insulin, glucagon, and others) reached US$ 548 billion in 2013." (PMID 25852997, 2015). "It is a relatively rare but important subtype of unexpected hypoglycemia in insulin-treated patients with diabetes even after they have stopped insulin administration." (PMID 25961056, 2015). "The partner in Zambia also stated that it “showed people involved [in diabetes] the challenges” adding that this was specifically with regards to insulin access and healthcare worker training." (PMID 26427953, 2015). "Of note, the expression of insulin was observed in different human primary cell types and that makes us to re-design our investigations related to insulin and its linkage with diabetes in future studies." (PMID 25743104, 2015). "In the Type 1 diabetes mellitus (T1DM) with a strong insulin deficiency, despite the increased hormone transport across the blood–brain barrier (BBB), the concentration of insulin in the brain is nevertheless very low." (PMID 28031898, 2015). "This study adds to the literature by showing a link of exogenous insulin use in patients with diabetes to breast cancer mortality." (PMID 26171401, 2015). "Median duration of diabetes was 6 (3.0-12.0) years, and 15.6% were using insulin and 76.6% other medications (principally metformin and sulfonylureas) for diabetes." (PMID 25855488, 2015). "The most common prescribed association was biguanide-sulfonamide (91.2%), and we noticed that 10.6% of participants wrongly use oral anti-diabetic drugs instead of insulin to manage diabetes emergencies." (PMID 25881080, 2015).
diabetes (continued). "While ZnT8 plays a significant role in insulin biology and therefore represents an attractive target for diabetes therapy, the other members of the zinc transporter family in diabetes are less defined." (PMID 25983752, 2015). "Insufficient insulin supply, resulting from beta-cell dysfunction and/or death, leads to chronic hyperglycemia and favor the development of diabetes mellitus, the most common metabolic disorder worldwide." (PMID 25880779, 2015). "Satisfaction with the latest-generation insulin pump (LGIP) was assessed in patients with diabetes mellitus enrolled in the Comparing Perception of Insulin Therapies for T1D Patients with the Aim to Improve Quality of Care (CHOICE) study." (PMID 29632571, 2015). "Our finding proved the ability of ZnONPs alone or in combination with insulin to approximately alleviate the bad effect of diabetes on serum testosterone levels." (PMID 26581756, 2015). "Availability and affordability of insulin is a well-recognised problem in low and middle-income countries, with the additional costs of syringes and other diabetes commodities adding to the treatment burden." (PMID 25947094, 2015). "Whole grain products and legumes are rich in fiber and improve insulin sensitivity and protect against the development of diabetes by slowing down carbohydrate digestion and decreasing the glycemic index." (PMID 25752843, 2015). "Using a physiologically relevant dose of insulin, we have detected early signs of insulin resistance prior to the development of glucose intolerance and overt diabetes-like phenotypes." (PMID 25713323, 2015). "Debbie’s clinician reiterates the need for Debbie to use her insulin to improve her diabetes and suggests that attending the diabetes class will give her the confidence she needs to use the insulin and that this will improve her fatigue." (PMID 27417747, 2015). "Insulin resistance continues to progress until beta cells begin to cease functioning, insulin levels drop, and overt diabetes ensues." (PMID 25961053, 2015). "Activation of stress-sensitive kinases like p38 and ERK 1⁄2 stimulates the serine phosphorylation of 1RS-1/IRS-2 which reduces insulin-stimulated IRS-1 tyrosine phosphorylation and insulin sensitivity which triggers the early onset of diabetes." (PMID 26839808, 2015). "The experimental setting of an induced hypoglycemia mimics an acute complication in patients with diabetes mellitus (both type 1 and type 2), which results from over dosage of insulin, some other antidiabetic drugs, or for example, stresses." (PMID 26564063, 2015). "In the adjusted analysis being under insulin treatment (OR = 3.24; 95% CI: 1.56–6.75), diabetes duration (OR = 1.23; 95% CI: 1.16–1.31) and age (OR = 1.05; 95% CI: 1.02–1.08) were independently associated with DR." (PMID 25925666, 2015). "These nanoparticle conjugates were found to be viable carrier for personal insulin delivery to treat diabetes." (PMID 26498972, 2015). "The efficacy of medicinal mushrooms in the treatment of diabetes by protecting against β-cell damage through enhanced antioxidant defenses, reduced inflammation, and increased insulin release has been reported." (PMID 26221612, 2015). "PIO is an anti-diabetic insulin-sensitizing agent that improves insulin action in a variety of animal models of insulin resistance and diabetes." (PMID 25523934, 2015). "This held true also after adjustment for fibrinogen, HbA1c, diabetes duration and insulin treatment." (PMID 25928628, 2015). "Although we did not measure insulin levels in this study, an increase in plasma insulin has previously been reported in diet-induced models of diabetes." (PMID 26035391, 2015). "In this context, a means of expanding insulin-secreting β-cells would be highly beneficial in the treatment of diabetes." (PMID 26038943, 2015).
diabetes (continued). "Researchers have demonstrated the advantages of glucose sensors and closed-loop insulin delivery approaches in facilitating the diabetes treatment to make it beneficial in both type 1 and type 2 diabetes." (PMID 26273667, 2015). "Continuous subcutaneous insulin infusion (CSII) or an insulin pump is a viable choice for patients with diabetes mellitus who require close-to-physiologic insulin treatment." (PMID 25785276, 2015). "Deregulation of insulin secretion and IIS activity have been implicated in diseases such as diabetes and cancer." (PMID 26710087, 2015). "We previously demonstrated that vglycin ameliorates diabetes in a T2DM Wistar rat model by improving insulin sensitivity and glucose tolerance." (PMID 26510947, 2015). "There were 4 patients (10.5%) who required subcutaneous insulin therapy to correct the hyperglycemia, and all these subjects had preexisting type 2 diabetes mellitus." (PMID 26681940, 2015). "This would be consistent with 11β-HSD1-/- mice showing increased insulin but decreased glucose levels, and with the emerging importance of glucagon and α-cells in the etiology of diabetes mellitus." (PMID 26305481, 2015). "Genetic dissection of different forms of monogenic diabetes sheds light on beta cell physiology and improved understanding of insulin secretion and its regulation." (PMID 26300908, 2015). "In other fields, such as treatment of diabetes mellitus this closed-loop control is already solved; known as artificial pancreas (continuous glucose sensor for measurements, insulin pump for infusion and control algorithm)." (PMID 26540189, 2015). "Db/db mice were used as an in vivo model of diabetes; palmitate (PA)-stimulated HepG2 cells were used as an in vitro cell model with impairment of insulin signaling." (PMID 25909991, 2015). "Hypoglycemia is a common side effect of insulin therapy for diabetes for people with type 1 and type 2 diabetes." (PMID 28702227, 2015). "Diabetes mellitus is a common metabolic disorder characterized by dysfunction of insulin-secreting pancreatic beta-cells." (PMID 25880779, 2015). "Specific results from the RAPIAs were viewed as important, such as the calculations of life expectancies and also highlighting the issue of access to diabetes care and insulin from a personal view." (PMID 26427953, 2015). "In contrast, studies show that G0 levels and insulin concentrations are slightly higher in the morning than their overnight “basal” levels, especially for participants with diabetes." (PMID 25881031, 2015). "Therapies for improving or enhancing insulin sensitivity will hopefully bring beneficial clinical effects on the metabolic disorders and lifestyle-related diseases including obesity and diabetes." (PMID 25922845, 2015). "Type 2 diabetes constitutes 90–95% of all diabetes cases and results from insulin resistance, inadequate compensatory insulin secretory response, or both." (PMID 26074958, 2015). "The major limitation is that in both cohorts, participants differed by both diabetes status and the HLA-DRB1*02 haplotype associated with higher insulin secretion." (PMID 26606528, 2015). "Three were already known to have diabetes (all on insulin treatment); we diagnosed five new cases of diabetes and 61 of prediabetes (40 IFG and 21 IGT) at this follow-up." (PMID 25940643, 2015). "Diabetes is characterized by high glucose level in blood due to either less insulin secretion from pancreas or developing insulin resistance in skeletal muscle." (PMID 26273671, 2015). "Type 1 diabetes mellitus (T1DM) results from the autoimmune destruction of insulin-producing β-cells in the pancreas, leading to dysregulation of blood glucose levels." (PMID 26110898, 2015). "Initiation of insulin treatment generally entails increased diabetes-related health care contacts and treatment costs, and decrease in health care costs." (PMID 28702235, 2015).